TGFB1 (transforming growth factor beta 1)
Diseases named in the same sentence as TGFB1 in open-access papers (continued):
Sharing a sentence is not in itself a finding about the gene and the disease.
Cognitive impairment (64 papers, 2013 to 2026). Abnormal cognition is characterized by deficits in thinking, reasoning, or remembering. "The likely important role of inflammation in cognitive impairment among HCV-infected patients is further supported by a recent study demonstrating that the effect of TGFB1 polymorphism on cognitive functions is influenced by the presence of viral hepatitis." (PMID 40184345, 2025). "Despite existing knowledge, few studies have examined TGFB1's role in viral hepatitis‐associated cognitive impairment." (PMID 38970443, 2024). "These behavioral data indicate that loss of microglia-derived TGFB1 not only impacts aging-associated trajectories but also promotes hippocampal-dependent cognitive impairments characteristic of age-related functional decline in an age-dependent manner." (PMID 38645176, 2024). "Functionally, loss of microglia-derived TGFB1 resulted in hippocampal-dependent cognitive impairments in an age-dependent manner, suggesting that advancement through aging-associated trajectories may facilitate age-related cognitive decline." (PMID 38645176, 2024). "Additionally, a Brazilian study found that the +25G>C (rs1800471) polymorphism, associated with lower TGFβ1 production, was more common in individuals with cognitive impairment, supporting the association between lower TGFβ1 levels and AD risk." (PMID 38970443, 2024). "It is hypothesized that the interaction between TGFB1 genetic polymorphisms and the viral hepatitis‐induced inflammatory microenvironment may lead to altered inflammatory responses, resulting in different levels of cognitive impairment." (PMID 38970443, 2024). "Disruptions in TGFβ1 signaling, particularly through its effects on Smad proteins and interactions with pathways such as MAPK and PI3K, have been linked to neurodegenerative diseases and cognitive impairments." (PMID 38970443, 2024). "Furthermore, recent investigations have demonstrated that hsa-mir-106a-5p which based on our results is linked to (TGFB1, ITGB1, and CXCR4), reduces the level of VEGFA, a protective factor against cognitive impairment in AD patients." (PMID 37705610, 2023). "In conclusion, combined with the results of the literature search and bioinformatic analysis, we believe that the three genes, BIRC6, TGFB1, and PSEN1, have a clear correlation with T2DM and cognitive impairment, which can be used as target genes for disease prediction in the future." (PMID 37189611, 2023). "Cumulatively, these results strongly suggest that one of the mechanisms by which LAP alleviates adenine-induced cognitive impairment may via modulating SNCA- and/or TGFB1- mediated neuroinflammation." (PMID 36969810, 2023).
nasopharyngeal carcinoma (63 papers, 2010 to 2025). A carcinoma arising from the nasopharyngeal epithelium. "In nasopharyngeal carcinoma, EGR3 is activated under hypoxia and contributes to immunosuppression and tumor growth through regulation of IL10 and TGFB1 in regulatory B cells." (PMID 40649712, 2025). "Actually, similar metabolic shift has also been observed in nasopharyngeal carcinoma CNE1 cells during TGFβ1-induced EMT (data not shown)." (PMID 35414781, 2022).
sarcoma (62 papers, 2009 to 2025). A usually aggressive malignant neoplasm of the soft tissue or bone. "Analysis of the TCGA sarcoma dataset suggested that TGFB1 mRNA expression (z-score) was positively correlated with COL1A1 expression (P < 0.0001, Pearson r: 0.3991)." (PMID 39574893, 2024). "Evidence for the mechanism of CAF development in the sarcoma biology was obtained from our RNA-seq data that revealed overexpression of TGFB1 in both GIST cells and CAFs." (PMID 33568624, 2021). "The negative correlations between the expression of IL-33 and CCL20 and TGFB1 were then validated by analysis using GSE6481 or GSE967 datasets of sarcoma." (PMID 29896199, 2018). "Cell‐cell communication analysis showed that SD3 enriched sarcoma cell subtype sarco_2 had low expression of HLA‐DRA, HLA‐E, HLA‐F and HLA‐A, and high expression of ICAM1 and TGFB1." (PMID 39658531, 2024). "In our CLL cohort, CD5+CD19+CD27+ cells represented the discriminant phenotypic features of IL10+vs- and TGFβ1+vs- subsets, which also resembled CD19+CD81+CD27+CD25+PD-L1hi tumor evoked Bregs producing both IL10 and TGFβ1 in sarcomas." (PMID 36973425, 2023). "Levels of IL-1β, IL-4, IL-6, CXCL5, CXCL12, CXCL14, MIF, IGF-1, TGFβ-1, and CCL21 were increased in one or more sarcoma cohorts compared with controls, and levels of IL-15 and IL-16 were significantly lower in one or more sarcoma cohorts compared to healthy controls." (PMID 41008853, 2025).
esophageal cancer (61 papers, 2011 to 2026). A primary or metastatic malignant neoplasm involving the esophagus. "This is the first report to reveal that Rac3 is implicated in TGFβ1-induced E-cadherin down-regulation in esophageal cancer cells." (PMID 24684802, 2014). "Over-expression of TGFβ1 in esophageal cancer is associated with advanced stage of disease and poor prognosis." (PMID 24684802, 2014). "TGFβ1 is associated with poor prognosis of esophageal cancer." (PMID 24684802, 2014). "Expression of TGFβ1 is associated with poor prognosis of esophageal cancer." (PMID 24684802, 2014). "The expression of proinflammatory M1 macrophage genes such as IL1β and TNFα were significantly downregulated in esophageal carcinoma tissues, while M2 marker genes TGFβ1 and MRC1 were upregulated." (PMID 34612767, 2021). "Here we investigate the role of FBXL19-mediated Rac3 degradation in TGFβ1-induced E-cadherin down-regulation in esophageal cancer cells." (PMID 24684802, 2014). "Here, we show that TGFβ1 treatment (4 days) induces E-cadherin down-regulation in a dose dependent manner in esophageal cancer cell line OE19." (PMID 24684802, 2014). "This study is the first to report that Rac3 regulates TGFβ1-mediated E-cadherin down-regulation in esophageal cancer cells, indicating a critical role of Rac3 in the progress of esophageal cancer." (PMID 24684802, 2014). "Over-expression of FBXL19 attenuated TGFβ1-induced E-cadherin down-regulation and esophageal cancer cells elongation phenotype." (PMID 24684802, 2014). "Further, we demonstrate that FBXL19 negatively regulates Rac3-mediated TGFβ1 signaling in esophageal cancer." (PMID 24684802, 2014). "Further, we found that TGFβ1 reduced E-cadherin expression in another esophageal cancer cell line OE33 (up to ~69%)." (PMID 24684802, 2014). "Further, we found that Rac3 plays a critical role in TGFβ1-induced E-cadherin down-regulation in esophageal cancer cells." (PMID 24684802, 2014). "Esophageal cancer cells (OE19 and OE33) were used to investigate TGFβ1-induced E-cadherin down-regulation by Immunoblotting and Immunostaining." (PMID 24684802, 2014). "This study discovered that Rac3 plays an important role in the progress of esophageal cancer cells and the FBXL19 may function as a tumor suppressor through its ability to reduce Rac3 levels and inhibits TGFβ1 pathway." (PMID 24684802, 2014). "It has been shown that TGFβ1 expression is higher in esophageal cancer tissues, compared to normal squamous epithelium and non-malignant Barrett’s mucosa." (PMID 24684802, 2014).
metastatic carcinoma (61 papers, 2007 to 2025). A carcinoma which has spread from the original site of growth to another anatomic site. "Considering the promoted role of TGFβ-1 in metastatic cancers, we investigated TGFβ-1 gene expression level." (PMID 34012911, 2021). "However, the TGFβ1 levels in primary cancer are commonly lower than in metastatic cancer, which therefore may affect the correlation analysis." (PMID 31991845, 2020). "Overall, TGFB1-mediated, EZH2-catalyzed SMAD3 K53/K333 methylation could function as a predictive marker of survival for patients with cancer and potentially serve as a therapeutic target for patients with metastatic cancer." (PMID 35085106, 2022).
malignant glioma (59 papers, 2006 to 2025). A grade III or grade IV glioma arising from the central nervous system. "Wogonin and Scutellaria ocmulgee leaf extract (SocL) both inhibit TGFβ1 secretion and reduce TGFβ1 induced Treg activity in malignant gliomas, thereby reversing tumor-mediated immunosuppression." (PMID 36439106, 2022). "Meanwhile, by inducing autophagy, astrocyte elevated gene 1 (AEG-1) can improve malignant glioma cell resistance to transforming growth factor-beta 1 (TGF-β1)-induced epithelial-mesenchymal transition (EMT)." (PMID 34204169, 2021). "Currently, there are several phase I/III clinical trials using antisense TGF-β oligonucleotides that inhibit TGFβ-1 (AP 12009) in patients with recurrent high-grade glioma." (PMID 33138229, 2020). "Previous studies have reported that there was elevated expression of TGFβ1 and TGFβ2 in both blood serum and tumor tissues of patients with malignant glioma." (PMID 32974124, 2020). "In contrast, some other studies suggest that constitutive AhR activity positively controls TGFβ1, TGFβ2, and LTBP-1 in malignant glioma cells." (PMID 24795504, 2014). "This gene can induce transforming growth factor beta 1 (TGF-β) signaling, followed by nuclear factor kappa B (NF-κB) mediated matrix metallopeptidase 2/9 (MMP2/9) overexpression orchestrating migration, invasion and epithelial–mesenchymal transition in malignant glioma cells of human origin." (PMID 37335084, 2023).
non-alcoholic steatohepatitis (58 papers, 2008 to 2025). "Nevertheless, no alteration in the expression of pannexin 1 (Panx1, recently related to inflammation in non-alcoholic steatohepatitis and to liver damage) or the fibrosis markers transforming growth factor β1 (Tgfb1) or desmin (Des) was observed." (PMID 33374541, 2020). "The precise mechanism of TGFβ1 signaling in the progression of non-alcoholic steatohepatitis (NASH) has remained unclear." (PMID 23441159, 2013). "In HFD-fed mice, we found nonalcoholic steatohepatitis, increased gene expression of TNFα, IFNγ, MCP-1, caspase-3, TGFβ1 and collagen α1(I), and increased levels of 3-tyrosine nitrated proteins." (PMID 25261569, 2014).
parasitemia (58 papers, 2009 to 2025). "Inosine, a purine nucleoside, proved to be the most effective agent at improving peripheral blood parasitemia from a group of agents tested, including TGFβ1, dexamethasone, and IL-10." (PMID 21483851, 2011).
ischemic stroke (56 papers, 2012 to 2026). A stroke disorder caused by obstruction of blood flow to the brain, due to thrombotic (local blood clot formation) or embolic (due to a blood clot or other material traveling from another site) event. "In the non-hypertensive group, CCL11 rs3744508, LTC4S rs730012, FCER1B rs569108, TGFB1 rs1800469, LTA rs909253 and CCL11 rs4795895 were associated with ischemic stroke." (PMID 22769019, 2012). "Increased expression of TGFβ1 is also observed in human brain tissue after ischemic stroke." (PMID 34572573, 2021). "Based on its pleiotropic function, it is not surprising that TGFβ (TGFβ1-3) plays an important role in recovery from ischemic stroke." (PMID 34572573, 2021).
Crohn disease (54 papers, 2006 to 2025). A gastrointestinal disorder characterized by chronic inflammation involving all layers of the intestinal wall, noncaseating granulomas affecting the intestinal wall and regional lymph nodes, and transmural fibrosis. "Therefore, herbs-partitioned moxibustion combined with acupuncture can prevent intestinal epithelial mesenchymal transition by inhibiting abnormal expression of TGFβ1, TβR2, Smad3, and Snail in the TGF-β1-Smad-Snail pathway in Crohn's disease." (PMID 31275422, 2019).
injury (54 papers, 2009 to 2026). Damage inflicted on the body as the direct or indirect result of an external force, with or without disruption of structural continuity. "Conversely, TGFβ1 signaling via TGFβR/SMAD-2/3 activation is pro-inflammatory in the context of mild traumatic brain injury." (PMID 30940161, 2019). "Earlier studies have reported that transforming growth factor beta 1(TGFβ1) is a critical mediator of hyperoxia-induced acute lung injury (HALI) in developing lungs, leading to impaired alveolarization and a pulmonary phenotype of bronchopulmonary dysplasia (BPD)." (PMID 25591994, 2015). "We identified Tgfb1 producing macrophages as a critical link between inflammation and aberrant mesenchymal differentiation, it is expressed by recruited macrophages and its absence in myeloid cells significantly attenuated the aberrant formation of HO after musculoskeletal trauma." (PMID 32024825, 2020). "Oral administration of stearic acid (SA) displayed protective effects in cholestasis-induced liver injury in rats, decreasing the accumulation of leukocytes, MPO activity, activation of NF-κB, and production of transforming growth factor-beta 1 (TGF-β1)." (PMID 39339251, 2024).
myelofibrosis (54 papers, 2014 to 2025). A partial or complete replacement of the bone marrow stroma by fibrous tissue. "Three genes implicated in myelofibrosis were found to be overexpressed in HLC: FGF2 (fibroblast growth factor-2; 500-fold), its receptor FGFR1 (50-fold), and TGFB1 (tumor growth factor ß1; 16-fold)." (PMID 35476232, 2022). "However, clinical studies examining bone marrow samples from patients have failed to establish a direct correlation between increased TGFβ-1 expression and the degree of myelofibrosis in MPN." (PMID 38339265, 2024). "The significance of TGFβ-1 in the fibrogenic process of PMF was demonstrated in a TGFβ-1−/− animal model, where overexpression of thrombopoietin (TPO) failed to induce myelofibrosis, in contrast to the severe bone marrow fibrosis developed in control wild-type mice." (PMID 38339265, 2024).
ovarian tumor (54 papers, 1999 to 2026). "In fact, a low level of TGFβ1 mRNA expression in advanced ovarian tumors was associated with better prognosis." (PMID 28758950, 2017). "However, whether CCAT1 is implicated in TGFβ1-induced EMT of ovarian tumor cells remains unclear." (PMID 30250403, 2018). "Here, we reveal that CCAT1 contributes to TGFβ1-induced EMT of ovarian tumor cells through miR-490-3p/TGFR1 axis." (PMID 30250403, 2018). "In sum, these data indicated that CCAT1 played its roles in TGFβ1-induced EMT of ovarian tumor through enhancing TGFβR1 expression." (PMID 30250403, 2018). "Taken together, these findings demonstrate that miR-675 expression suppresses primary ovarian tumor growth and metastasis in part by targeting the TGFβ1, inhibiting EMT through attenuating the TGFβ pathway, suggesting the potential of miR-675 as a therapeutic strategy for OC patients." (PMID 39744561, 2025). "An enhanced expression of EMT and metabolism regulators including G6PD and AKR1B1 and TGFβ1 observed in vitro in carboplatin resistant cell line was confirmed in platinum resistant and relapsed human ovarian tumor samples, compared to chemo naïve human tumors." (PMID 36463238, 2022). "It remains unknown about whether CCAT1 regulates TGFβ1-induced EMT of ovarian tumor cells through miR490-3p." (PMID 30250403, 2018). "Two functions (cell-to-cell signaling and interaction, and cellular growth and proliferation, and two upstream regulators (TGFB1 and IFNG) were shared between differentially expressed genes in the isogenic cell lines and differentially expressed genes in BRCA1-deficient vs. normal ovarian tumors." (PMID 31840082, 2019). "We demonstrated that TGFβ1 is enriched in CAF exosomes, which are transferred to ovarian tumor cells, inducing EMT through SMAD signaling." (PMID 29221185, 2017).
renal failure (54 papers, 2007 to 2025). "Our mouse model has now shown that sustained overexpression of HIF-2α alone is sufficient to induce tubulointerstitial fibrosis and renal insufficiency, perhaps partly mediated by induction of TGFb1." (PMID 22299048, 2012). "Direct blockade of TGFβ protein by chronic administration of anti-TGFβ1 antibodies has been shown to decrease renal insufficiency." (PMID 17319955, 2007). "Since the level of transforming growth factor beta 1 (TGFβ1) is increased in the plasma/serum of patients with kidney failure and CKD mice, and it also mediates EndMT, we further examined whether JMJD3 was involved in the process of TGFβ1-induced EndMT." (PMID 35278430, 2022). "Likewise, the expression of transforming growth factor beta‐1 (Tgfb1) was significantly less in double KO compared to Pkd1 KO mice at 10 weeks and showed a similar trend at kidney failure." (PMID 31038742, 2019).
cholangiocarcinoma (53 papers, 2013 to 2026). A carcinoma that arises from the intrahepatic biliary tree (intrahepatic cholangiocarcinoma) or from the junction, or adjacent to the junction, of the right and left hepatic ducts (hilar cholangiocarcinoma). "Most notably, miR-30b/c has been reported to influence transforming growth factor beta 1-induced epithelial to mesenchymal transition and biliary development and infection, while miR-200b, -204, and −320 have been linked to cholangiocarcinoma." (PMID 24138927, 2013). "It has been reported that TFAP2A can be involved in the EMT process in multiple ways, for example, by binding of TFAP2A to the TGFB1 promoter in HCCC cholangiocarcinoma cell lines." (PMID 39994865, 2025). "Consistent with the results of the 10x Genomics single-cell sequencing technology in human cholangiocarcinoma, ELISA and qPCR showed that TGFβ1 was dramatically upregulated in intracellular and supernatant of M2 macrophages compared with MΦ/M1 macrophages." (PMID 35033156, 2022). "In the present study, we analyzed the correlation between transforming growth factor beta 1 (TGF-β1) expression and prognosis in intrahepatic cholangiocarcinoma." (PMID 25993985, 2015). "M2 macrophage-derived TGFβ1, in particular, have been shown to induce EMT and drug resistance in cholangiocarcinoma cells via the atypical protein kinase C iota-mediated NF-κB signaling pathway." (PMID 39068459, 2024). "Indeed we found that chronic Tgfβ1 overexpression induced both HCC and cholangiocarcinoma (CCA), bile duct epithelial cell cancer, with dose-dependent severity." (PMID 34680297, 2021). "Surprisingly, TGFB1 were significantly dysregulated in almost all cancer types: it was significantly up-regulated in 17 cancer types such as AML, breast invasive carcinoma (BRCA), and cholangiocarcinoma (CHOL), whereas it was significantly down-regulated in 12 cancer types." (PMID 37925591, 2023).
head and neck cancer (53 papers, 2002 to 2025). A primary or metastatic malignant neoplasm affecting the head and neck. "Background and Objective: Studies have been conducted to explore the association between the single nucleotide polymorphisms (SNPs) in transforming growth factor beta 1 (TGF-β1) and head and neck cancer (HNC) susceptibility, however the findings are still inconclusive." (PMID 29163637, 2017). "TGFβ1 stimulates the phosphorylation of SMAD (Sma and Mad proteins), MAPK, and Akt in head and neck cancer but stimulated the migration of cancer cells in an Akt-dependent manner." (PMID 32731484, 2020). "TGFB1 can also enhance PD-L1 expression and treatment with a TGF-β1 receptor kinase inhibitor can downregulate PD-L1 expression in head and neck cancer, suggesting that targeting the EMT process could reverse the immunosuppressive tumor microenvironment." (PMID 36901697, 2023).